RUNX1 (RUNX family transcription factor 1)
Diseases named in the same sentence as RUNX1 in open-access papers (continued):
Sharing a sentence is not in itself a finding about the gene and the disease.
Hirschsprung disease (1 paper, 2022). Hirschsprung disease (HSCR) is a congenital intestinal motility disorder that is characterized by signs of intestinal obstruction due to the presence of an aganglionic segment of variable extent in the terminal part of the colon. "The modulation of COL6A1 and COL6A2 expression after RUNX1 silencing could explain the causal link between trisomy 21 and an increased incidence of Hirschsprung’s disease in DS." (PMID 35356434, 2022).
HIV-1 infection (1 paper, 2014). The type species of lentivirus and the etiologic agent of acquired immunodeficiency syndrome (AIDS). "To determine the relevance of RUNX1 expression in HIV-1 infection in human hosts we compared RUNX1 expression to viral load and CD4+ T-cell counts in viremic HIV-1 patients who were not on therapy." (PMID 24651404, 2014). "In order to determine the relevance of RUNX1 expression in HIV-1 infection in human patients we examined the expression of RUNX1, CBF-β and RUNX3 in primary T-cells." (PMID 24651404, 2014). "We next tested the effect of RUNX1 and CBF-β on spreading HIV-1 infection of Jurkat T-cells." (PMID 24651404, 2014).
Immunodeficiency syndromes (1 paper, 2024). "Immunodeficiency syndromes such as SCID and CVID are linked to RUNX1 mutations." (PMID 39132148, 2024).
intrahepatic cholangiocarcinoma (1 paper, 2022). A carcinoma that arises from the intrahepatic bile duct epithelium in any site of the intrahepatic biliary tree. "In intrahepatic cholangiocarcinoma, a study reported that lncRNA-NEF was dramatically downregulated in tumor tissues and upregulated lncRNA-NEF repressed cell migration and invasion by inhibition of runt-related transcription factor 1 (RUNX1)." (PMID 35573683, 2022).
ischemia (1 paper, 2024). A hypoperfusion of the BLOOD through an organ or tissue caused by a PATHOLOGIC CONSTRICTION or obstruction of its BLOOD VESSELS, or an absence of BLOOD CIRCULATION. "In this model, the blocked coronary artery is subsequently opened following a period of ischemia, as would be the case for treating patients with percutaneous coronary intervention, further supporting the translational potential of RUNX1." (PMID 38862712, 2024).
ischemic heart disease (1 paper, 2024). "Although the previous focus of RUNX1 research has been predominately in cancer and hematological field, recent evidence suggests that Runx1 plays a critical role in ischemic heart disease." (PMID 38862712, 2024).
joint diseases (1 paper, 2021). "However, the potential role of Runx1 in joint diseases is not well known." (PMID 34876557, 2021).
laryngeal carcinoma (1 paper, 2024). Carcinoma that arises from the laryngeal epithelium. "The staining of laryngeal cancer tissue microarrays shows that the expression of RUNX1 in patient tissues is positively correlated with the number of VMs." (PMID 38610001, 2024). "In addition, staining of laryngeal cancer tissue microarrays revealed an overexpression of RUNX1 in patient tissues, with a notably higher expression in stage IV patients than that in patients at stages I–III." (PMID 38610001, 2024).
latent infection (1 paper, 2023). "During latent infection of EBV, RUNX3 is a direct target of the viral transcription factor EBNA2 and the induced RUNX3 protein binds to the conserved RUNX binding site near the TSS of RUNX1 P1 promoter, leading to the repression of RUNX1." (PMID 37032358, 2023).
leprosy (1 paper, 2020). Leprosy is a chronic infectious disease affecting primarily the skin and peripheral nervous system. "IHC tests corroborated that the increase of Runx-1 in leprosy patients is linked to the presence of macrophages marked with CD68 in the inflammatory infiltrate." (PMID 32265900, 2020). "Runx-1 expression was increased in 33.3% of leprosy skin samples and in 100% of non-leprosy samples." (PMID 32265900, 2020). "On the other hand, immunostaining showed that the overexpression of Runx-1 in leprosy patients was due to its expression in the cells present in the dermal inflammatory infiltrate." (PMID 32265900, 2020). "We found evident changes in the expression of two of the evaluated genes: Hes-1, downregulated 2.32 times, and Runx-1, upregulated 3.69 times in leprosy skin samples." (PMID 32265900, 2020). "The results of the increased transcription of Runx-1 in the cutaneous samples of leprosy patients allow us to consider two hypotheses in this respect." (PMID 32265900, 2020). "The dermis showed a median of 98.5 cells stained for Runx-1 per field observed in leprosy patients (interquartile range (IQR) = 44.7–177 cells per field), while the median was only 4 cells per field in non-leprosy patients (IQR= 1.5–5.5 cells per field) (p < 0.0001)." (PMID 32265900, 2020). "Therefore, the aim of this study was to establish the relationship between the expression of components of the Notch signaling pathway (Hes-1, Hey-1, Runx-1, Jagged-1, Notch-1, and Numb) with tissue changes in the skin and dermal nerve fibers of leprosy patients." (PMID 32265900, 2020). "At the level of the eccrine glands, a percentage of Runx-1-positive cells greater than 75% was observed in 63.3% of the eccrine structures of leprosy samples and in 73.3% of those of non-leprosy samples, a non-significant difference (p > 0.05)." (PMID 32265900, 2020). "Differences in the expression of Runx-1 in eccrine glands and hair follicle between leprosy skin and non-leprosy skin." (PMID 32265900, 2020). "We established that Runx-1 transcription factor is not expressed in the dermal nerves of leprosy patients." (PMID 32265900, 2020). "In the visualized hair follicles, the percentage of Runx-1-positive cells was greater than 75% in 50% of the hair follicles of leprosy samples and in 75% of non-leprosy samples, a slight but non-significant (p > 0.05) reduction in leprosy samples." (PMID 32265900, 2020). "On the other hand, based on the inflammatory mechanism explaining the reduction of Hes-1, we ask the question: why was the transcriptional factor Runx-1 not altered in leprosy patients, considering that some Notch transcription factors are affected in inflammatory environments?" (PMID 32265900, 2020).
Limb ataxia (1 paper, 2026). A kind of ataxia that affects movements of the extremities. "In mice, Runx1 knockout abolishes definitive haematopoiesis, Runx2 deficiency impairs bone formation, and Runx3 loss leads to limb ataxia due to neuronal death during embryogenesis." (PMID 41550415, 2026).
liver diseases (1 paper, 2025). "As a conclusion, the RUNX1 mechanism of action in liver diseases is based on the upregulation of its downstream genes, including VEGFs, adhesion molecules, and chemokines." (PMID 41226441, 2025). "It has been suggested that RUNX1 targeting could overcome the exacerbation of FA-related liver diseases." (PMID 41226441, 2025).
luminal A breast carcinoma (1 paper, 2017). A biologic subset of breast carcinoma defined by high expression of genes characteristic of luminal epithelial cells, including estrogen receptor (ER), estrogen regulated protein LIV-1, and the transcription factors hepatocyte nuclear factor 3, HNF3A, XBP1, and GATA 3. "Intact Runx1 function is also important for Luminal A breast cancer." (PMID 28407681, 2017).
male pattern baldness (1 paper, 2020). "Out of 13 SNPs included in our predictive models for hair greying, 6 (FGF5 rs7680591, RUNX1 rs68088846, IRF4 rs12203592, BRINP1 rs2416699, TEX41 rs10928235, GRID1 rs2814331) were previously associated with male pattern baldness (MPB)." (PMID 32758128, 2020).
meningioma (1 paper, 2020). A generally slow growing tumor attached to the dura mater. "Similarly, the roles of RUNX1, STAT5, and TWIST1 in meningioma remain poorly understood, and could represent novel therapeutic targets." (PMID 33093491, 2020).
metastatic disease (1 paper, 2023). "Targeting RUNX1 may be an attractive strategy to potentiate the anti-tumor effects of AR inhibition, specifically in the slow-growing CSC-like populations that resist chemotherapy which lead to metastatic disease." (PMID 36766786, 2023).
mixed phenotype acute leukemia (1 paper, 2022). An acute leukemia of ambiguous lineage. "Furthermore, single-cell omics has been used to reveal epigenetic alternations in mixed phenotype acute leukemia (MPAL), in which RUNX1 may act as a potential oncogene, resulting in poor survival of MPAL patients." (PMID 35318612, 2022).
myocarditis (1 paper, 2023). Myocarditis is a condition that is characterized by inflammation of the heart muscle (myocardium). "Considering that adult cardiomyocytes proliferate in myocarditis in a STAT3‐dependent manner, it would be informative to examine whether STAT3/Runx1 is activated by inflammatory reaction in adult cardiomyocytes." (PMID 38040660, 2023).
myonecrosis (1 paper, 2015). "Our study of Runx1 function in the muscle’s response to myonecrosis reveals that this transcription factor is activated and cooperates with the MyoD and AP-1/c-Jun transcription factors to drive the transcription program of muscle regeneration." (PMID 26275053, 2015). "Thus, muscle Runx1, which is not expressed during development or in resting WT muscle, is activated in response to either neuronal-mediated muscle damage, or myonecrosis." (PMID 26275053, 2015).
nephrolithiasis (1 paper, 2017). The presence of a calculus in the pelvis of the kidney; this is most often composed of mineral salts and proteins. "Genes encoding for Runx1, Runx2, KRT 18, KRT 8, VIM, Fn-1, Col1a1 and Col1a2 were up regulated during hyperoxaluric conditions and further increased after crystal deposition or nephrolithiasis." (PMID 29091707, 2017).
Neurodevelopmental delay (1 paper, 2025). "Overlapping large interstitial deletions involving 21q22 that include dosage-sensitive genes such as RUNX1 have been associated with neurodevelopmental delay, dysmorphism, and hematologic abnormalities, and contiguous-gene 21q22 deletions of comparable size (~7–8 Mb) have been reported previously." (PMID 41300732, 2025).
non-Hodgkin lymphoma (1 paper, 2022). Distinct from Hodgkin lymphoma both morphologically and biologically, non-Hodgkin lymphoma (NHL) is characterized by the absence of Reed-Sternberg cells, can occur at any age, and usually presents as a localized or generalized lymphadenopathy associated with fever and weight loss. "Here, we predicted that RUNX1 may be an effective target in Non-Hodgkin Lymphoma, and that the residues of RUNX1 that are involved in interacting with Ibrutinib are also in proximity to the DNA binding interface of RUNX1." (PMID 36090034, 2022). "A drug compound that is directed towards RUNX1 is Ibrutinib, which affects signaling of the B cell antigen receptor (BCR) in the case of Non-Hodgkin Lymphoma." (PMID 36090034, 2022).
normocytic anemia (1 paper, 2023). Anemia in which the red blood cell volume is normal. "A potentially pathogenic germline variant in the runt‐related transcription factor 1 (RUNX1) gene was discovered by a focused 51‐gene myeloid malignancy panel during investigation for his unexplained normochromic normocytic anemia." (PMID 37701147, 2023).
oesophageal cancer (1 paper, 2019). "In studies of oesophageal cancer, RUNX1a, a transcript of RUNX1, has been shown to promote cell proliferation and tumour growth." (PMID 31370857, 2019).
olfactory neuroblastoma (1 paper, 2021). An olfactory neuroblastoma arising in the paranasal sinus. "Runx1 induction in olfactory neuroblastoma cell line JFEN is associated with TrkA expression, and this correlates with specific in vivo expression of Runx1 and TrkA in DRG nociceptive neurons." (PMID 34440820, 2021).
oncocytic tumours (1 paper, 2009). "An independent microarray data set showed the overexpression of ELK1, RUNX1 and ESRRA in the thyroid oncocytic tumours." (PMID 19536094, 2009).
osteopetrosis (1 paper, 2021). Osteopetrosis, also known as marble bone disease, is a descriptive term that refers to a group of rare, heritable disorders of the skeleton characterized by increased bone density on radiographs. "TGF-β plays a role in the coupling of bone formation to bone resorption, thus the severe osteopetrosis phenotype observed in Runx1 CKO mice could be due to loss of TGF-β-mediated coupling of osteoblast-mediated bone formation and osteoclast-mediated bone resorption." (PMID 33476325, 2021).
ovarian endometrioid carcinoma (1 paper, 2013). "The implication of RUNX1 in EOC tumorigenesis is currently unknown, although it was shown that in conjunction with some matrix metalloproteinases (MMP-2 and -9) RUNX1 could contribute to the invasive stage of endometrial and ovarian endometrioid carcinomas." (PMID 24124450, 2013).
Parasitemia (1 paper, 2019). "Parasitemia was positively correlated with IFN-γ, T-BET, RUNX1, and STAT1 and negatively correlated with NFκB factor." (PMID 31614626, 2019).
Parkinson disease (1 paper, 2016). A progressive degenerative disorder of the central nervous system characterized by loss of dopamine producing neurons in the substantia nigra and the presence of Lewy bodies in the substantia nigra and locus coeruleus. "Other studies also suggest the involvement of CHIP in regulating the levels of other Hsp90 client proteins such as runt-related transcription factor 1 (Runx1) and LRRK2, via UPS, a protein whose mutation is linked to Parkinson’s disease." (PMID 27757073, 2016).
pemphigus (1 paper, 2023). Pemphigus is a group of rare autoimmune diseases that cause blistering of the skin and mucous membranes (mouth, nose, throat, eyes, and genitals).This conditioncan occur at any age, but often strikes people in middle or older age. "As regards RUNX1, the overexpression of miR-338-3p leads to a reduction in the expression of RUNX1 and its dependent transcription factor, FOXP3, in CD4+ cells, which contributes to the dysfunction of regulatory T cells observed in the course of pemphigus." (PMID 37298095, 2023).
pituitary tumor (1 paper, 2019). A benign or malignant neoplasm affecting the pituitary gland. "If in mice, as in human pituitary tumors, Runx1 controls Galectin-3 protein expression, then Runx1 controls microglia morphology in vivo through Galectin-3 as our present findings suggest." (PMID 30930748, 2019). "First, that transcription factors Runx1 and Runx2 regulate Galectin-3 expression in human pituitary tumors." (PMID 30930748, 2019).
PN tumors (1 paper, 2023). "In comparison to primary PN tumors, MES tumors showed significantly elevated levels of USP10 and RUNX1." (PMID 36949071, 2023).
pneumonia (1 paper, 2023). An acute, acute and chronic, or chronic inflammation focally or diffusely affecting the lung parenchyma, caused by an infection in one or both of the lungs (by bacteria, viruses, fungi, or mycoplasma.). "Recent studies have shown that RUNX1 is highly expressed in lung interstitial and epithelial cells, and plays a key role in lipopolysaccharide-induced pneumonia by regulating the NF-κB pathway." (PMID 37153149, 2023).
polycythemia (1 paper, 2022). Abnormally high mass or concentration of red blood cells in the blood, either due to an increase in erythropoiesis or a decrease in plasma volume. "Functional analyses showed an association between p.P138L and an increase in the expression of HIF-regulated genes SLC2A1, TFRC, and HK, as well as RUNX1/AML1 and NF-E2, which are increased in acquired and primary polycythemia, respectively." (PMID 35205407, 2022).
post-traumatic stress disorder (1 paper, 2024). An anxiety disorder precipitated by an experience of intense fear or horror while exposed to a traumatic (especially life-threatening) event. "Stress susceptibility of this transcription factor has also been supported by studies revealing Runx1 upregulation in stress-defeated mice and discovering that RUNX1 was a shared susceptibility gene between post-traumatic stress disorder (PTSD) and MDD." (PMID 39457114, 2024).
prostate tumors (1 paper, 2016). "Further, men with castration resistant PCa and androgen-independent mouse prostate tumors upregulate Runx1." (PMID 27634876, 2016). "The presence of miRNAs targeting Runx1 and/or Runx2 in normal prostate tissue and the complete absence of these miRNAs in prostate tumors upregulates both Runx1 and Runx2 as well as AKT signaling." (PMID 27634876, 2016).
pulmonary oedema (1 paper, 2026). "Cardiomyocyte-specific tamoxifen-inducible Runx1-deficient mice with HFpEF are protected, with preservation of diastolic function, and attenuation of pulmonary oedema, exercise intolerance, and hypertrophy." (PMID 42190056, 2026).
RASopathies (1 paper, 2025).
rectal tumor (1 paper, 2024). "In our study, FOXP3(r = 0.179), CD72(r = 0.155), RUNX1(r = 0.327), LAG3(r = 0.194), CTLA4(r = 0.236) have a positive correlation with AP3M2 in Colon Neoplasm, but no irrelevancy in rectal tumor." (PMID 38177168, 2024).
Renal neoplasm (1 paper, 2019). The presence of a neoplasm of the kidney. "Therefore, we may speculate that RUNX1/PRMT1 co-expression may be significant for the favorable behavior of renal neoplasms." (PMID 31655611, 2019).
respiratory failure (1 paper, 2023). The significant impairment of gas exchange within the lungs resulting in hypoxia, hypercarbia, or both, to the extent that organ tissue perfusion is severely compromised. "Mice lacking Runx1 die as embryos from hematopoietic failure and mice lacking Runx2 exhibit neonatal lethality from respiratory failure." (PMID 36766843, 2023).
Right ventricular hypertrophy (1 paper, 2025). In this case the right ventricle is more muscular than normal, causing a characteristic boot-shaped (coeur-en-sabot) appearance as seen on anterior- posterior chest x-rays. "A PH mouse model was used to investigate the impacts of RUNX1 knockdown on hemodynamics, right ventricular hypertrophy (RVH), and pulmonary artery remodeling (hematoxylin–eosin [H&E] staining)." (PMID 39151099, 2025).
SARS-CoV infection (1 paper, 2012). "A comparative study by microarray analysis of host gene transcription in the Huh7 cell line infected with SARS-CoV and human coronavirus 229E found significantly increased RUNX1 expression with SARS-CoV infection as compared to human CoV22E." (PMID 22253733, 2012).
Sjogren syndrome (1 paper, 2017). An autoimmune disorder in which immune cells attack and destroy the glands that produce tears and saliva. "Although direct association of Runx1 in pathogenesis of Sjogren syndrome has not been reported, a part of downstream molecular pathway might be shared in development of the disease." (PMID 28877240, 2017).
temporal lobe epilepsy (1 paper, 2024). A localization-related (focal) form of epilepsy characterized by recurrent seizures that arise from foci within the temporal lobe, most commonly from its mesial aspect. "Microglial activation and phenotypic switching play a critical role in neurological disease, and in temporal lobe epilepsy (TLE) mouse model and in BV2 cells, RUNX1 may play a critical role in microglial phenotype through the Notch1 signaling pathway." (PMID 38385040, 2024).
tendinopathy (1 paper, 2016). "Thus, the increase of Runx-1 caused by KGN is likely responsible for the appearance of more chondrocytes in our KGN-induced tendinopathy model because Runx-1 has been shown to play a critical role in chondrogenesis and chondrocyte proliferation." (PMID 26848746, 2016).